MTOR (mechanistic target of rapamycin kinase)
Diseases named in the same sentence as MTOR in open-access papers (continued):
Sharing a sentence is not in itself a finding about the gene and the disease.
glaucoma (20 papers, 2013 to 2025). Increased pressure in the eyeball due to obstruction of the outflow of aqueous humor. "Also, GBE is involved in the activation of the adenosine monophosphate-activated protein kinase (AMPK) signalling pathway, affecting NFκB, mTOR, Nrf-2, and Wnt/β-catenin signalling pathways, which are implicated in the pathogenesis of glaucoma." (PMID 39951447, 2025). "Pathway analysis of differentially spliced transcripts from Group 1 showed enriched pathways related to eIF2 and mTOR signalling (both implicated in glaucoma pathogenesis), as well as eIF4 signalling (implicated in multiple sclerosis), and leukocyte extravasation signalling." (PMID 30670050, 2019). "Little data are published in regards to everolimus application in glaucoma surgery, but the study investigating prolonged drug delivery of sirolimus (also mTOR inhibitor similar to everolimus) revealed promising results." (PMID 36015676, 2022). "A great deal of studies have provided evidence showing the involvement of the mTOR signalling pathway in the pathogenesis of glaucoma." (PMID 35883796, 2022). "First, we produced only in vitro data; in vivo studies to assess the effectiveness of mTOR inhibitors in a glaucoma model are required." (PMID 34239027, 2021). "So far, no study has reported on the link between p38-MAPK, p42/44-MAPK, and the PI3K/mTOR signaling pathway in glaucoma." (PMID 33375386, 2020). "Protein kinase C (PKC), mitogen-activated MAPK kinases (p38 and p42/44-MAPK), and the PI3K/mTOR axis are key Ca2+ signal transducers in fibrosis and we therefore investigated their expression and activity in normal and glaucoma cultured LC cells." (PMID 33375386, 2020). "We also found elevated mRNA expression of mRNA expression of PI3K, IP3R, mTOR, and CaMKII in glaucoma LC cells." (PMID 33375386, 2020). "In contrast, treatment with rapamycin, an inducer of autophagy via the mechanistic target of rapamycin (mTOR) pathway, rescues apoptosis in mouse RGCs expressing the glaucoma mutant E50K." (PMID 29875767, 2018). "Induction of autophagy by a partial inhibition of the mTOR pathway in oxidatively stressed trabecular meshwork cells has a possible role in the pathogenesis of glaucoma." (PMID 28902914, 2017). "Although this inherited retinal degeneration does not share the same common pathological processes with other ocular neurodegenerative diseases, such as AMD, DR, and glaucoma, that are induced by oxidative stress, hypoxia, and inflammation, mTOR plays a critical role in the pathogenesis of RP." (PMID 35883796, 2022). "As such, targeting mTOR in those diseases could be the novel treatment in such disease, and for the glaucoma patients, we speculated that inhibition of mTOR could be a novel treatment in glaucoma patients." (PMID 34239027, 2021). "Moreover, shikonin has been shown to alleviate oxidative stress and neurodegenerative damage associated with glaucoma, which may be achieved through the inhibition of the AKT/mTOR pathway." (PMID 40808675, 2025). "Some novel agents for wound healing modulation in glaucoma surgery are being investigated nowadays, among which are immunosuppressants with selective mechanism of action–calcineurin inhibitor cyclosporine A (CsA) and inhibitor of mechanistic target of rapamycin (mTOR) everolimus." (PMID 36015676, 2022). "Interfering with the Rac1/mTOR signaling pathway may provide a new strategy for treating glaucoma." (PMID 32913260, 2020). "Additionally, mTOR is important for axonal regeneration in glaucoma and traumatic optic neuropathy wherein the deletion of the Phosphatase and Tensin Homolog (PTEN), a negative regulator of mTOR, promotes robust retinal ganglion cell (RGC) axon regeneration within the injured optic projection." (PMID 32066462, 2020). "This review highlights the critical role of immune-mediated processes and dysregulated signaling pathways, such as VEGF, NF-κB, JAK-STAT, MAPK, and PI3K/Akt/mTOR, in the pathogenesis of DR, DME, DK, diabetic cataract, and glaucoma." (PMID 39457658, 2024).
glaucoma (continued). "This is in line with the finding that, mTOR inhibitor abates TGF‐β2‐induced fibrotic changes in trabecular meshwork cells and increases aqueous outflow in glaucoma treatment." (PMID 36227401, 2023). "Data are the average of three biological replicates comparing transcription of PI3K, mTOR, IP3R and CaMKII between normal controls to the age-matched glaucoma LC cells." (PMID 33375386, 2020). "The average data of PI3K, mTOR, IP3R and CaMKII, transcription was detected at low levels in normal control LC cells, but significantly (* p < 0.05), up-regulated in glaucoma LC cells." (PMID 33375386, 2020). "In this study, we found elevated levels of mRNA expression level of PI3K, mTOR, IP3R, and CaMKII, in glaucoma LC cells." (PMID 33375386, 2020). "Inhibitors of mTOR, though not well-studied in glaucoma surgery yet, also revealed better results in the case of long-term application compared to single administration." (PMID 36015676, 2022). "We explored whether mTOR inhibitors reduced ECM remodeling and TM cell fibrosis, both of which are thought to play roles in the pathogenesis of glaucoma." (PMID 34239027, 2021). "Inhibitors of PI3K/Akt/mTOR pathway have been extensively investigated in cancer therapy Therefore, PI3K/Akt/mTOR axis may have a central role in regulating the over-expression of ECM genes and over-proliferation found in glaucoma LC cells." (PMID 33375386, 2020). "Our hypothesis may suggest a new target for combating the optic nerve damage in glaucoma, by interfering with downstream steps such as the PKC, MAPK, and PI3K/mTOR signaling pathways." (PMID 33375386, 2020). "Here, we provide evidence of a possible coordination between PKCα, p38-, and p42/44-MAPK and/or the downstream PI3K/Akt/mTOR axis (all related to Ca2+ signaling) to promote the excess of pro-fibrotic ECM production and LC cell over-proliferation found in glaucoma." (PMID 33375386, 2020).
insulinoma (20 papers, 2013 to 2025). "The mammalian target of rapamycin (mTOR) pathway has also been implicated in insulinoma tumorigenesis." (PMID 40648766, 2025). "Everolimus, an oral mTOR inhibitor, has been used for malignant insulinomas associated with refractory hypoglycemia." (PMID 36494838, 2022). "The mTOR pathway is involved in insulinoma pathogenesis, and mTOR inhibitors such as everolimus have been explored as a treatment option with some success." (PMID 40648766, 2025). "Everolimus, a mammalian target of rapamycin (mTOR) inhibitor, has a proven antiproliferative effect in patients with metastasized insulinomas." (PMID 41561059, 2025). "Sirolimus, an inhibitor of mammalian target of rapamycin (mTOR), has been used in some children with HI resistant to conventional medical therapies, based on reports of beneficial responses in adults with insulinoma." (PMID 37454648, 2024). "The intracellular mTOR pathway is involved in β-cell growth and altered insulin secretion in patients with insulinoma, ketone body synthesis, and insulin action." (PMID 39153498, 2024). "Because of abnormal activation of the mammalian target of rapamycin (mTOR) pathway in several neoplasms, including insulinoma, mTOR inhibitors have been increasingly recognized as a treatment option in patients with CHI." (PMID 27181099, 2016). "We determined how 2-DG and/or melatonin affected known regulators of insulin signaling, phosphoinositide 3-kinase (PI3K), Akt/PKB, and mTOR, in rat insulinoma INS-1E cells." (PMID 27493704, 2016). "mTOR pathway activity (as measured by immunohistochemistry staining for p-S6) appeared to be significantly higher only in copy-neutral insulinomas, independent of YY1 mutation." (PMID 39456803, 2024). "Similarly, the RIP-myrAKT transgenic mouse model induces insulinoma formation by upregulation of the AKT/mTOR pathway." (PMID 33126717, 2020). "Fortunately insulinoma patients in such severity are very rare and mTOR inhibitors like everolimus may be promising, but studies with more patients are required to support this proposal." (PMID 23738155, 2013). "However, mTOR pathway-related genes were frequently amplified in another insulinoma subtype." (PMID 39456803, 2024). "One female patient presenting with hypoglycemia secondary to metastatic ACC was trialed on everolimus, an mTOR inhibitor previously shown to be effective in the management of insulinoma-induced hypoglycemia, with no clinical response." (PMID 40270996, 2025). "Recently, the mTOR inhibitor everolimus appears to exert a specific hyperglycaemic effect in metastatic insulinomas irrespective of its effect on tumor growth." (PMID 29349087, 2017). "Lastly, to confirm the relationship of insulin production with autophagy and EDC3 protein, we investigated whether the mTOR inhibitor, rapamycin, induced autophagy and expression of GRP78/BiP and EDC3 proteins in rat insulinoma INS-1E cells." (PMID 27493704, 2016).
laryngeal squamous cell carcinoma (20 papers, 2012 to 2025). A squamous cell carcinoma that arises from the larynx. "Furthermore, high mTOR expression has been claimed to be associated with a worse outcome in laryngeal squamous cell carcinomas that have been subjected to postoperative radiotherapy." (PMID 24593867, 2014). "Higher FADS1 levels in the lung tissues were associated with LUAD risk, which is consistent with its role in increasing the proliferation and migration of laryngeal squamous cell carcinoma through activation of the Akt/mTOR pathway." (PMID 37236969, 2023). "MiR-145-5p elevated the autophagy flux of laryngeal squamous cell carcinoma via activating the Akt/mTOR pathway to suppress cancer advancement." (PMID 35369850, 2022). "FADS1 has emerged as mediator of lipid metabolism gene and drives laryngeal squamous cell carcinoma progression by activating AKT/mTOR signaling pathway." (PMID 33277966, 2021). "FADS1 can promote the progression of laryngeal squamous cell carcinoma by activating the AKT/mTOR signaling pathway." (PMID 34706720, 2021). "Some studies have pointed out that the Akt-mTOR signaling pathway, downstream of PRKCI, promotes the malignant progression of laryngeal squamous cell carcinoma and inhibits autophagy." (PMID 39015499, 2024).
multiple sclerosis (20 papers, 2008 to 2025). A progressive autoimmune disorder affecting the central nervous system resulting in demyelination. "It is possible that synaptopathy, which occurs in multiple sclerosis, is associated with dysfunction of the regulatory components of local translation – mTOR signaling and FMRP, which regulates the efficiency of dendritic mRNA translation." (PMID 32921299, 2020). "This article recapitulates the evidence on the role of mammalian targets of rapamycin (mTOR) complex pathways in multiple sclerosis (MS)." (PMID 35897651, 2022). "Secondly, no significant decrease in PRMT5 protein levels was observed upon treatment with an mTOR inhibitor in MM, whereas this was previously reported in T-cell expansion in a murine multiple sclerosis model." (PMID 35757005, 2022). "Preclinical and clinical studies anticipating a beneficial role for mTOR inhibitors in patients with multiple sclerosis have prompted us to evaluate the potential use of Rapamycin in the context of MS." (PMID 29492193, 2018). "Importantly, the study of mTOR pathway contributions to autoimmune inflammatory demyelination and multiple sclerosis illustrates the difficulties in the clinical application of animal model results." (PMID 35897651, 2022). "mTOR inhibitors or knockout in animal of multiple sclerosis." (PMID 35897651, 2022). "Similarly, mTOR is aberrantly overactivated in dysfunctional Tregs isolated from relapsing–remitting multiple sclerosis patients." (PMID 36352020, 2022). "In addition, CXCR2 counteracts adult OPC differentiation and myelination potential, in a model of multiple sclerosis, by interfering with the PI3K/AKT/mTOR pathway, thereby strongly reinforcing the possibility of a role of cytokines and chemokines in OPC maturation blockade, during development." (PMID 36513635, 2022).
tauopathy (20 papers, 2011 to 2026). Neurodegenerative disorders involving deposition of abnormal tau protein isoforms (tau proteins) in neurons and glial cells in the brain. "Abnormal activation of mTOR signaling have been recently implicated in the pathophysiology of AD and other neurodegenerative disease, including such as autophagy, tauopathy, and Aβ metabolism." (PMID 33967735, 2021). "Our results suggested that there was an increase of autophagy-related markers, coincident with the inhibition of the Akt/mTOR pathway at late-stage (30 days) post-ischemia, when reduced the tauopathy and decreased neuronal loss in the CI model." (PMID 26042033, 2015). "Also, MTOR-mediated cell-cycle activation causes neurodegeneration in a Drosophila tauopathy model." (PMID 23817674, 2013). "From a molecular point of view, the ribosome apparatus and mTOR signalling are crucial in tauopathy." (PMID 41516328, 2026). "In a Drosophila Tauopathy model, mTOR activation was found to mediate cell cycle reentry and neurodegeneration and blocking mTOR signaling rescued Tau-mediated toxicity in such flies." (PMID 34215308, 2021). "For example, genetically increasing mTOR signaling can upregulate tau level and promote tau phosphorylation, but reducing mTOR signaling with rapamycin can ameliorate tau pathology and rescue motor deficits in a mouse model of tauopathy." (PMID 30934958, 2019). "Consistent with in vivo experiment, in vitro results suggest that mTOR signaling regulates tau phosphorylation and the activation of mTOR enhances tau-induced neurodegeneration in a Drosophila model of tauopathy." (PMID 30934958, 2019). "Conversely, autophagy enhancers like rapamycin (an mTor inhibitor) or trehalose (an mTor-independent autophagy activator) can promote the degradation of insoluble tau in mouse models of tauopathy." (PMID 26936765, 2016). "A very recent study has suggested that methylene blue induces macroautophagy to attenuate tauopathy through inhibiting mTOR activation." (PMID 23653592, 2013). "In this view, mTOR/S6 pathway could be a potential therapeutic target to ameliorate translational impairments and, consequently cognitive disfunctions related to tauopathy progression." (PMID 41516328, 2026). "Given that impaired translational control can disrupt synaptic plasticity and memory, Tau-induced alterations in protein synthesis may contribute to tauopathy progression and identify mTOR signalling as a potential therapeutic target." (PMID 41516328, 2026). "In addition, the alteration of GSK3β and mTOR signaling plays a crucial role in tauopathy, which directly or indirectly participated in regulation of tau phosphorylation." (PMID 33967735, 2021). "This new insight into the pharmacodynamics of mTOR inhibitors in regulation of neuronal autophagy may contribute to development of therapies for tauopathies." (PMID 32591533, 2020). "Constitutive overexpression of mTor, (mammalian Target of rapamycin), a key negative regulator of the autophagic pathway, prevents activation of the autophagy pathway and increases the levels of hyperphosphorylated tau in a cell model of tauopathy." (PMID 26936765, 2016). "However, the mechanism of tauopathy mediated by mTOR is still unclear." (PMID 33967735, 2021). "Pharmacological studies in human tauopathy animal models via the administrations of autophagy inducers (trehalose and methylthioninium chloride), or mTOR inhibitors (rapamycin, bexarotene, and galectin) support the notion that the involvement of autophagy in Tauopathy may be beneficial." (PMID 29991349, 2018). "Conversely, from a long-term perspective, our findings indicate that the effects of metformin on tau phosphorylation and aggregation could be dissociated through chemical modifications and point to AMPK/mTOR signaling as a potential druggable target for tauopathy." (PMID 26858121, 2016).
tauopathy (continued). "Taken together, our findings maybe could support that the autophagic related markers indicate that this degradation pathway could be involved in reverses tauopathy, promotes cellular homeostasis, and plays a neuroprotective role via the inhibition of the mTOR pathway in late-stage of 2-VO CI model." (PMID 26042033, 2015). "One reason we evaluated an mTOR inhibitor and autophagy stimulator as a protectant for the perforant pathway is the reported beneficial effects of stimulators of autophagy on neuropathology and behavior for other regions of the central nervous system in experimental models of tauopathy." (PMID 26540269, 2015). "Notably, pharmacological studies using autophagy inducers such as trehalose and dimethyl sulfoxide, or mTOR inhibitors like rapamycin, bexarotene, and lactacystin in animal models of human tauopathy support the notion that autophagy involvement in Tauopathy may confer beneficial effects." (PMID 37927337, 2023). "Secondly, it has been reported that the activation of mTOR enhanced the expression levels of p70S6K and p4E-BP1 which further lead to the tauopathy." (PMID 33967735, 2021). "For example, PI3K/mTOR signaling regulates tau phosphorylation and TOR activation enhances tau-induced neurodegeneration in a Drosophila model of tauopathies." (PMID 21980451, 2011). "We identified that capsaicin could potently inhibit mTOR activity in cells and mice, supporting TRPV1 activation as a potential intervention for neuronal damage in tauopathy." (PMID 37641913, 2024). "This study, for the first time highlights the role of Chico – the ortholog of mammalian IRSs in playing a crucial role in reducing tau hyperphosphorylation and aggregation in our tauopathy models by controlling the downstream tau kinases GSK-3β and ERK and modulating the mTOR/autophagy pathways." (PMID 31427921, 2019). "Since we have used 0–3 days old adult flies for this study, it is possible that our tauopathy model represents an early stage of pathology during which the PI3K/AKT/mTOR signaling pathway is not yet activated." (PMID 31427921, 2019).
bipolar disorder (19 papers, 2015 to 2026). A disorder of the brain that causes unusual shifts in mood, energy, activity levels and the ability to carry out day-to-day tasks. "mTOR dysfunction is implicated in various disorders, including bipolar disorder where studies have found its activity to be decreased in brain and blood samples." (PMID 36504683, 2022). "Akt‐mammalian target of rapamycin (mTOR) signaling was reduced in the prefrontal cortex in a subset of bipolar disorder subjects." (PMID 41510670, 2026). "Research has found that patients with acute bipolar affective disorder have decreased expression of the AKT1/mTOR (Alpha serine/threonine-protein kinase/Mammalian target of rapamycin) gene during depressive episodes." (PMID 38791423, 2024). "Lithium, a drug clinically used to treat bipolar disorders, is an autophagy modulator acting via a mammalian target of rapamycin (mTOR)‐independent pathway." (PMID 35028271, 2022). "mTOR may also serve as a convergence point between the acute antidepressant effects of ketamine and the longer-term prophylactic effects of lithium in bipolar disorder, since a key mechanism of the latter involves GSK3β inhibition, an upstream regulator of mTOR activity." (PMID 41304907, 2025). "mRNA expression of AKT1 and mTOR are downregulated in bipolar depression, and may induce autophagy." (PMID 34122166, 2021). "Few changes were identified following this treatment, although four proteins—FAM163A, RIN1, mTOR and MCCC1—shown to be dysregulated in bipolar disorder were dysregulated in the same direction by haloperidol treatment, suggesting that these effects may have been drug treatment-related." (PMID 27898073, 2016).